SRGAP3 (SLIT-ROBO Rho GTPase activating protein 3)
Description:
GTPase-activating protein for RAC1 and perhaps Cdc42, but not for RhoA small GTPase. May attenuate RAC1 signaling in neurons.
Synonyms: WRP; ARHGAP14; KIAA0411; MEGAP; SRGAP2
Tractability: PROTAC: ubiquitination databases record sites on it; its protein half-life has been measured.
Gene: Protein-coding gene on chromosome 3 (8,980,591 to 9,363,053, reverse strand). Ensembl gene ENSG00000196220.
Subcellular location (Human Protein Atlas): Cytosol; Basal body; Centrosome
Pathways (Reactome):
Signal Transduction: CDC42 GTPase cycle; RAC1 GTPase cycle
Developmental Biology: Inactivation of CDC42 and RAC1
Gene Ontology:
Molecular function: protein binding; GTPase activator activity
Biological process: negative regulation of cell migration; nervous system development; regulation of small GTPase mediated signal transduction; regulation of synapse assembly; signal transduction
Cellular component: postsynapse; cytosol; synapse
Genetic constraint (gnomAD): Loss-of-function variants: 39 observed, 124.56 expected, observed/expected ratio (o/e) 0.31, 90% interval 0.24 to 0.41. The upper end of that interval is the gene's LOEUF score, 0.41, which puts it in group 1 of 6, group 1 being the genes least tolerant of losing a copy. Missense variants: 1,213 observed, 1,489.8 expected, observed/expected ratio (o/e) 0.81, 90% interval 0.78 to 0.85. Synonymous variants: 601 observed, 574.03 expected, observed/expected ratio (o/e) 1.05, 90% interval 0.98 to 1.12.
Homologues: Orthologues: chimpanzee SRGAP3 (100% identical), dog SRGAP3 (99% identical), mouse Srgap3 (99% identical), macaque SRGAP3 (97% identical), rat Srgap3 (96% identical), pig SRGAP3 (95% identical), guinea pig SRGAP3 (95% identical), tropical clawed frog rad18 (88% identical), zebrafish srgap3 (85% identical), Caenorhabditis elegans srgp-1 (28% identical). Paralogues in human: SRGAP1 (68% identical), SRGAP2 (58% identical), ARHGAP4 (39% identical), SRGAP2B (29% identical), SRGAP2C (28% identical).
Diseases named in the same sentence as SRGAP3 in open-access papers:
SRGAP3 is named in the same sentence as 29 diseases in open-access papers, as found by Europe PMC text mining. Sharing a sentence is not in itself a finding about the gene and the disease. The quoted sentences say what the papers report.
mental retardation (10 papers, 2007 to 2024). "Loss of the srGAP3 in humans has been linked to mental retardation, and deletion of the srGAP3 in mice impairs learning and memory by affecting dendritic spine formation." (PMID 26499801, 2015). "SRGAP3 (MEGAP) is a small GTPase involved in the Slit-Robo pathway which plays a role in neuronal development and has been implicated in X-specific mental retardation." (PMID 24647608, 2014). "Abnormalities in SRGAP3 have also been implicated in intellectual deficiency and Parkinson's disease." (PMID 23074677, 2011). "IAA was found to upregulate the protein nervous wreck (isoform 4), a Drosophila homolog of the human srGAP3/MEGAP protein associated with mental retardation, proposed to control synapse morphology by regulating actin dynamics downstream of growth signals in presynaptic terminals." (PMID 38594449, 2024). "In humans, SRGAP3 is also known as mental disorder-associated GAP protein (MEGAP) given its hypothesized role in chromosomal intellectual disability in the context of hemizygous loss of function." (PMID 37582857, 2023). "However, an SRGAP3 deficiency cannot explain all cases of intellectual disability in 3p deletion syndrome." (PMID 33643973, 2021). "In addition, srGAP3 was initially reported as mental disorder-associated GAP protein, also known as WAVE-associated Rac GTPase-activating protein (WRP), through the analysis of a female patient with 3p deletion syndrome who had hypotonia and severe intellectual disability." (PMID 33425915, 2020). "Genetic aberrations in two neuronal RhoGAPs, namely oligophrenin and MeGAP/srGAP3, had been found in two distinct types of human mental retardation." (PMID 17284314, 2007). "SRGAP3, alternate name of Mental-Disorder Associated GAP Protein (MEGAP) is reported to be disrupted and functionally inactivated by a translocation breakpoint in a patient with a severe form of mental retardation, the 3p- syndrome." (PMID 23505444, 2013).
schizophrenia (4 papers, 2011 to 2021). A major psychotic disorder characterized by abnormalities in the perception or expression of reality. "Case report identified the first family of a SRGAP3 copy number variant (CNV) in schizophrenia." (PMID 23505444, 2013). "The inverse F-BAR (IF-BAR) domain proteins srGAP1, srGAP2 and srGAP3 are implicated in neuronal development and may be linked to mental retardation, schizophrenia and seizure." (PMID 23505444, 2013). "Further investigation of association between SRGAP3 and schizophrenia is warranted." (PMID 23074677, 2011). "Additionally, the region of chromosome 3 containing SRGAP3 has been implicated in linkage studies of schizophrenia." (PMID 23074677, 2011). "This is the first family report of a SRGAP3 copy number variant (CNV) in schizophrenia." (PMID 23074677, 2011). "Mutations in SRGAP3 have been linked to several neurological disorders, including mental retardation, ASD, and schizophrenia." (PMID 34572042, 2021). "A study of another Srgap3 knock-out mouse model showed that lack of SrGAP3 resulted in various neuroanatomical and behavioral abnormalities linked to schizophrenia." (PMID 34572042, 2021). "SRGAP3 knockout mice lead to lethal hydrocephalus or ‘schizophrenia-related’ behaviors." (PMID 23505444, 2013). "This is the first family report of a SRGAP3 CNV in schizophrenia and related disorders." (PMID 23074677, 2011). "Here, we expand on our initial report of this discovery with subsequent cloning and sequencing of the duplication junction to investigate a SRGAP3 duplication that segregates with psychotic illness in the family of a patient with childhood onset schizophrenia (COS)." (PMID 23074677, 2011). "SRGAP3 abnormalities have been observed at the genomic and expression level in several brain disorders including mental retardation, Parkinson's disease, and schizophrenia although previous schizophrenia reports did not have family data." (PMID 23074677, 2011).
neuroblastoma (3 papers, 2013 to 2021). Neuroblastoma (NB) is the most common solid, extracranial childhood tumor. "Co-transfection of SrGAP3 and lamellipodin in fibroblasts and neuroblastoma cells resulted in an overall inhibition of lamellipodia formation and neurite outgrowth, demonstrating that SrGAP3 can inhibit lamellipodin-dependent actin protrusion." (PMID 34572042, 2021).
glioma (2 papers, 2021 to 2022). A benign or malignant brain and spinal cord tumor that arises from glial cells (astrocytes, oligodendrocytes, ependymal cells). "SRGAP3 has been implicated as a potential oncogenic driver in low-grade gliomas, when fused with RAF1, resulting in constitutive activation of the ERK/MAPK pathway, and altered expression of the SRGAP protein has been demonstrated in breast cancer." (PMID 33431066, 2021). "Finally, qRT-PCR confirmed that SH3GL2 and SRGAP3 expression levels in glioma tissues were significantly lower than those in normal brain tissues." (PMID 36408514, 2022).
allergic disease (1 paper, 2022). An immune response that occurs following re-exposure to an innocuous antigen, and that requires the presence of existing antibodies against that antigen. "SRGAP3 was never related to asthma or RC until the GWAS study carried out in 2011, and up to now no studies have reported its role in asthma or any allergic diseases." (PMID 35205259, 2022).
alveolar rhabdomyosarcoma (1 paper, 2021). A rapidly growing malignant mesenchymal neoplasm. "Although the functionality of these mutations has not been fully clarified, mutations in SRGAP3 and KMT2D have been detected and considered relevant in a variety of sarcomas, including angiosarcoma, endometrial stromal sarcoma and alveolar rhabdomyosarcoma." (PMID 34885165, 2021).
asthma (1 paper, 2022). "According to statistical analysis, 2 out of the 11 analysed SNPs were associated to asthma with a significant p-value: rs1162394 (gene SRGAP3) and rs25681 (gene C5), while both SNPs resulted in being not linked to RC manifestation." (PMID 35205259, 2022). "Two SNPs were found associated to asthma with a significant p-value: rs25681 in C5 gene (p = 0.044, OR = 1.34) and rs1162394 in SRGAP3 (p = 0.019, OR = 1.41)." (PMID 35205259, 2022). "Considering that sex was found to be associated with asthma in the whole allergic population, a logistic regression was performed adding sex as a covariate, and only rs1162394 in the SRGAP3 gene shows a significant nominal p-value (p = 0.015)." (PMID 35205259, 2022).
autism spectrum disorder (1 paper, 2023). A spectrum of developmental disorders that includes autism, and Asperger syndrome. "Two de novo missense variants in SRGAP3 were proposed to be related to Autism Spectrum Disorder in the Simons Simplex Collection." (PMID 37582857, 2023).
colorectal cancer (1 paper, 2021). A primary or metastatic malignant neoplasm that affects the colon or rectum. "All five patients in our cohort with SRGAP3-mutant tumors were characterized by an amino acid change at the identical position (1081) reported in colorectal cancer." (PMID 33431066, 2021).
dyslexia (1 paper, 2010). A learning disorder characterized by an impairment in processing written words. "SRGAP3 is a candidate for severe X-linked mental retardation and ROBO1 is a candidate for dyslexia." (PMID 20345892, 2010).
Insulin resistance (1 paper, 2015). Increased resistance towards insulin, that is, diminished effectiveness of insulin in reducing blood glucose levels. "We next investigated whether insulin resistance in the peripheral tissues affected the phosphorylation/dephosphorylation of srGAP3 in the brains of mice subjected to intraperitoneal insulin injection after a fast." (PMID 26499801, 2015).
mental disorder (1 paper, 2011). A disease that has its basis in the disruption of mental process. "Taken together, our findings and the studies cited above suggest that SRGAP3 may play an important role in neural development and that disruption or alteration of this gene may be partially etiologic for several mental disorders." (PMID 23074677, 2011).
neuroepithelial neoplasm (1 paper, 2022). A neoplasm of the nervous system that arises from the neuroepithelial tissues. "These included a truncating SRGAP3 mutation in a case without any clinically relevant calls by any modality and with a poorly characterized histological diagnosis (neuroepithelial neoplasm, NOS)." (PMID 35475276, 2022).
Obesity (1 paper, 2020). Accumulation of substantial excess body fat. "Interestingly, a lack of ATP10A activity in adulthood is related to obesity in humans and SRGAP3 expression is known to be influenced by its DNA methylation status." (PMID 33005172, 2020).
peripheral nerve injury (1 paper, 2023). Injury to a peripheral nerve. "In conclusion, the findings of this study suggest that EA can inhibit abnormal dendritic spine remodeling in the spinal dorsal horns of rats with peripheral nerve injury through the srGAP3/Rac1 signaling pathway and increase the mechanical pain threshold." (PMID 37211600, 2023). "In addition, EA can relieve neuropathic pain by regulating the plasticity of dendritic spines in the spinal dorsal horns of rats with peripheral nerve injury, and the srGAP3/Rac1 signaling pathway plays an important role in this process." (PMID 37211600, 2023).
cancer (6 papers, 2015 to 2023). A tumor composed of atypical neoplastic, often pleomorphic cells that invade other tissues. "Based on exome sequencing, 40 cancer-associated genes were found to be mutated in more than one sample, with SRGAP3 and KMT2D as the most common alterations (each in four cases)." (PMID 34885165, 2021). "Notably, two trunk genes (SPEN and ITK), a branch gene (SMARCE1), and several private genes (FAT4, CACNA1D, ATR, RUNX1T1, TERT, and SRGAP3) were defined as cancer-associated genes, according to the cancer gene census." (PMID 28716121, 2017). "To address whether the mutations found in our study could be causally implicated in ESS development, we queried the cancer Gene Census and found four mutations (SRGAP3, EBF1, IRF4 and PPARG)." (PMID 26429873, 2015). "Of them, SRGAP3 was co-detected in the cancer Gene Census and the pan-cancer database." (PMID 26429873, 2015). "Finally, in the pan-cancer database, we detected SRGAP3 and ZFP36L2 as putative cancer-related genes." (PMID 26429873, 2015).
tumor (3 papers, 2021 to 2022). "High expression of ARFIP2, SH3GL2, and SRGAP3 help maintain cell tension and stiffness as well as inhibit tumor invasion and metastasis." (PMID 36408514, 2022). "The product of SRGAP3 has been identified as having a tumor-suppressive role through the negative regulation of RAC, suggesting the presence of a dysregulated Rho GTPase pathway in CCSA." (PMID 34885165, 2021).
infection (1 paper, 2017). The state of being infected such as from the introduction of a foreign agent such as serum, vaccine, antigenic substance or organism. "The results showed that the viability and proliferation of NSCs decreased significantly when srGAP3 was knocked out (LV3-srGAP3 infection)." (PMID 29358957, 2017). "After culturing in a differentiation medium 7 days, the number of nestin and β-tubulin III-positive cells in the srGAP3 knockdown group was more than that of the control group (LV3-NC infection) and the number of GFAP-positive cells decreased." (PMID 29358957, 2017).
neurodevelopmental disorder (1 paper, 2011). A behavioral and cognitive disorder with onset during the developmental period that involves impaired or aberrant development of intellectual, motor, or social functions. "SRGAP3 abnormalities have been previously reported in several neurodevelopmental disorders." (PMID 23074677, 2011).
neurological disorders (1 paper, 2015). "Because srGAP3 and MARKs have been implicated in certain neurological diseases, we subsequently focused on the regulation of these proteins in this study." (PMID 26499801, 2015).
SRGAP3 also shares sentences with these, for which no sentence is quoted: allergic asthma (1 paper); angiosarcoma (1); breast carcinoma (1); endometrial stromal sarcoma (1); fibrosis (1); leukemia (1); neuropathic pain (1); Parkinson disease (1); sarcoma (1).